LINC01749 (long independently transcribed non-coding RNA 1749)
Gene: Long non-coding RNA gene on chromosome 20 (63,008,075 to 63,085,071, forward strand). Ensembl gene ENSG00000272259.
Diseases named in the same sentence as LINC01749 in open-access papers:
LINC01749 is named in the same sentence as 1 disease in open-access papers, as found by Europe PMC text mining. Sharing a sentence is not in itself a finding about the gene and the disease. The quoted sentences say what the papers report.
cancer (1 paper, 2023). A tumor composed of atypical neoplastic, often pleomorphic cells that invade other tissues. "Several of these lncRNAs in the risk model have been reported to play significant roles in different cancers, such as CCR5AS, LINC01749, TMEM220-AS1, KCNMA1-AS1, SNHG1, and LINC01672." (PMID 37686677, 2023).